BFSP2 (beaded filament structural protein 2)
Description:
Required for the correct formation of lens intermediate filaments as part of a complex composed of BFSP1, BFSP2 and CRYAA. Plays a role in maintenance of retinal lens optical clarity (By similarity).
Synonyms: CP47; CP49; LIFL-L; phakinin; CTRCT12; PHAKOSIN
Tractability: Antibody: UniProt places it where antibodies can reach, with medium confidence; its Gene Ontology location is reachable by antibodies, with medium confidence.
Gene: Protein-coding gene on chromosome 3 (133,400,056 to 133,475,222, forward strand). Ensembl gene ENSG00000170819.
Subcellular location: Cell membrane; Cytoplasm; Cytoplasm, cytoskeleton; Cytoplasm, cell cortex
Subcellular location (Human Protein Atlas): Cytosol; Plasma membrane
Gene Ontology:
Molecular function: protein binding; structural constituent of cytoskeleton; structural constituent of eye lens; structural molecule activity
Biological process: intermediate filament organization
Cellular component: cytoplasm; cytoskeleton; intermediate filament; plasma membrane; cell cortex
Genetic constraint (gnomAD): Loss-of-function variants: 39 observed, 47.72 expected, observed/expected ratio (o/e) 0.82, 90% interval 0.63 to 1.07. The upper end of that interval is the gene's LOEUF score, 1.07, which puts it in group 4 of 6, group 1 being the genes least tolerant of losing a copy. Missense variants: 525 observed, 564.15 expected, observed/expected ratio (o/e) 0.93, 90% interval 0.87 to 1. Synonymous variants: 197 observed, 223.41 expected, observed/expected ratio (o/e) 0.88, 90% interval 0.78 to 0.99.
Homologues: Orthologues: macaque BFSP2 (98% identical), dog BFSP2 (88% identical), pig BFSP2 (87% identical), rat Bfsp2 (86% identical), mouse Bfsp2 (85% identical), guinea pig BFSP2 (84% identical), rabbit BFSP2 (62% identical), chimpanzee BFSP2 (60% identical), tropical clawed frog bfsp2 (59% identical), zebrafish bfsp2 (52% identical). Paralogues in human: KRT14 (29% identical), KRT16 (29% identical), KRT10 (29% identical), KRT18 (29% identical), KRT17 (28% identical), KRT12 (28% identical), KRT15 (28% identical), KRT19 (27% identical), KRT36 (27% identical), KRT37 (27% identical), KRT38 (27% identical), KRT33B (27% identical), and 56 more.
Diseases named in the same sentence as BFSP2 in open-access papers:
BFSP2 is named in the same sentence as 15 diseases in open-access papers, as found by Europe PMC text mining. Sharing a sentence is not in itself a finding about the gene and the disease. The quoted sentences say what the papers report.
cataract (16 papers, 2008 to 2024). Partial or complete opacity of the crystalline lens of one or both eyes that decreases visual acuity and eventually results in blindness. "The importance of BFSP1 and BFSP2 was further evidenced by their mutation‐associated cataract phenotype." (PMID 28177569, 2017). "These mutations were mainly in exon 2; clinical types of cataracts induced by BFSP2 gene mutations are polymorphism cataracts, nuclear cataracts, cortical opacity Star cataracts, and gill-like cataracts etc.." (PMID 18958306, 2008). "BFSP1 and BFSP2 have been confirmed to be genes associated with autosomal dominant cataracts." (PMID 37974089, 2023). "We know from the previous report that BFSP1 and BFSP2 mutations can lead to congenital cataracts." (PMID 18958306, 2008). "In this study, a miRNA-mRNA network was constructed which contains miR-206-3p, miR-493-5p, miR-493-3p, miR-193b-3p, miR-200a-3p, miR-29a-3p, miR-29b-3p, miR-29c-3p, Bfsp1, Plp1, Cnp, Nfasc, Mbp, Pygm, Bfsp2 and Fn1, whose dysregulation may be associated with the cataract pathogenesis." (PMID 37974089, 2023). "The mechanism of how a mutation in BFSP2 can give rise to cataracts is unknown." (PMID 18958306, 2008). "Moreover, BFSP2 has been identified as a candidate gene in autosomal-dominant congenital cataracts and progressive cataract disease." (PMID 36658492, 2023). "Additionally, Hsf4, Tdrd7, gap junction protein epsilon 1 (Gje1), beaded filament structural protein 2 (Bfsp2), and lens intrinsic membrane protein 2 (Lim2) which are also significantly reduced in the SCR lens (<0.5-fold) were linked to human or animal cataracts (Supplement 1)." (PMID 33204712, 2020). "DHA levels on BFSP2 Cys326 and βA4-crystallin Cys5 in the UIF significantly increased from the C region to the IN region in lenses within each group: 18–22-year-old in BFSP2 Cys326, and 48–64-year-old with and without cataracts in βA4-crystallin Cys5." (PMID 38983090, 2023).
autosomal dominant congenital cataract (4 papers, 2008 to 2023). "There are five reported BFSP2 mutations that were found to induce formation of autosomal dominant congenital cataract." (PMID 18958306, 2008). "We first reported mutations in exon 5 of BFSP2, which can cause autosomal dominant congenital cataract, and BFSP2 mutations can also cause congenital lamellar cataracts." (PMID 18958306, 2008). "Mutations in BFSP2 have been reported to be associated with autosomal dominant congenital cataract." (PMID 18958302, 2008).
Age-related cataract (1 paper, 2011). A type of cataract (opacification of the lens) that forms during the course of aging. "Ephrin-A5(-/-) and EphA2(-/-) mice, maintained mainly in the C57BL/6J strain background with wild-type Bfsp2 (or CP49) genes, develop congenital or age-related cataracts with incomplete genetic penetrance that is consistent with previous reports." (PMID 22140528, 2011).
diabetes (1 paper, 2010). "API5, EDIL3, BFSP2, HNMT, and SCYL1BP1 were also among the top signals from the single-marker analysis within their associated region, but there is no clear connection currently between these genes and diabetes or its complications." (PMID 20871662, 2010).
lamellar cataracts (1 paper, 2008). "This novel mutation in exon 5 of BFSP2 appears to result in congenital lamellar cataracts." (PMID 18958306, 2008).
Microcornea (1 paper, 2010). A congenital abnormality of the cornea in which the cornea and the anterior segment of the eye are smaller than normal. "For example, mutations in multiple genes have been associated with cataract plus microcornea (e.g., MAF, CRYAA, and GJA8), posterior polar cataract (e.g., PITX3, EPHA2, CHMP4B, and NF2), or sutural cataract (e.g., BFSP2, CRYAB, and NHS)." (PMID 21042563, 2010).
myopia (1 paper, 2023). "Genetic disruption or depletion of BFSP2 will result in severe visual impairment, such as myopia, congenital cataract, loss of lens function in both human and mice." (PMID 37629073, 2023).
visual disorders (1 paper, 2016). "Eight positively selected genes within the tarsier lineage were implicated in several diseases associated with eye development and visual disorders (BBS2, BFSP2, IDUA, IL1A, IMPG1, RGR, SRD5A3 and TMC8)." (PMID 27708261, 2016).
BFSP2 also shares sentences with these, for which no sentence is quoted: tumor (2 papers); autosomal dominant cataracts (1); carcinoma (1); congenital cataracts (1); retinal degeneration (1); rhabdomyosarcoma (1); sarcoma (1).